CEP290 (centrosomal protein 290)
Diseases named in the same sentence as CEP290 in open-access papers (continued):
Sharing a sentence is not in itself a finding about the gene and the disease.
Joubert syndrome (60 papers, 2009 to 2025). Joubert syndrome (JS) is characterized by congenital malformation of the brainstem and agenesis or hypoplasia of the cerebellar vermis leading to an abnormal respiratory pattern, nystagmus, hypotonia, ataxia, and delay in achieving motor milestones. "Another group looking at CEP290 mutations in patients with Joubert syndrome found that CEP290 mutations cause RPE maturation defects as well, which precede photoreceptor degeneration." (PMID 39011458, 2024). "One of these genes is CEP290, a gene linked to Joubert Syndrome, which has been associated with multiple fetal anomalies, including macrocephaly, increased biparietal diameter, and ventriculomegaly, on fetal MRI and ultrasound." (PMID 39350038, 2024). "Biallelic mutations in the CEP290 gene cause early onset retinal dystrophy or syndromic disease such as Senior-Loken or Joubert syndrome." (PMID 37642804, 2023). "It is reported that kidney disease affects up to 1/3 of patients with Joubert syndrome and is more common in those with pathogenic variants in CEP290, TMEM67 and AHI1 genes." (PMID 35858853, 2022). "The Cep290-knockout (Cep290tm1Asw/tm1Asw, hereinafter referred to as KO) mouse is also a model for Joubert syndrome and was generated by inserting a β-gal-neoR cassette in place of exons 1–4 in the Cep290 allele." (PMID 34520396, 2021). "Apart from isolated blindness, mutations in the CEP290 gene can cause various syndromes like Bardett-Biedl syndrome, Meckel-Gruber syndrome, Senior-Loken syndrome, and Joubert syndrome." (PMID 33308271, 2020). "In this study, we first reported a novel causative mechanism of Joubert syndrome: a copy number variation (CNV) combined with a single-nucleotide variant in CEP290 gene, which can be helpful in the genetic diagnosis of this disease." (PMID 32600475, 2020). "We had two unrelated patients with different phenotypes but who were found to have the same homozygous nonsense variant NM_025114.3:c.5668G>T p.(Gly1890*) in CEP290 which had previously been described in Joubert syndrome patients." (PMID 31836858, 2020). "The cep290fh297/fh297 mutants were unable to breed and 100% of the mutants exhibit a severe scoliosis, a phenotype previously linked to defective cilia and a pathology has been reported in a a subset of Joubert Syndrome patients with CEP290 mutations." (PMID 30970040, 2019). "The SCA protein ataxin 10 interacts with the ciliary proteins NPHP5 (nephronophthisis 5) and CEP290 (centrosomal protein 290), and a patient with Joubert syndrome had a mutation of ataxin 10 itself." (PMID 31299042, 2019). "Recently, CEP290-associated cilia elongation has been described in primary renal epithelial cells from three individuals affected with Joubert syndrome." (PMID 31091803, 2019). "We note an interesting phenotype in FBP_29, who harbored reported compound heterozygous splicing variants in CEP290: a splicing variant that was reported to cause Joubert syndrome and the recurrent CEP290 deep intronic cryptic splice site variant." (PMID 29186038, 2017). "Morphants of the Joubert syndrome/nephronophthisis-associated protein Cep290 have certain defects with cerebellum morphology and have kidney cysts but both length and movement of the pronephric cilia is unaffected." (PMID 19254375, 2009). "Moreover, CEP290 has also been linked to Joubert syndrome, a primary ciliopathy presenting with a distinctive midbrain-hindbrain malformation, leading to motor and cognitive impairments that manifest in early life." (PMID 40924492, 2025). "Furthermore, knockdown of CDK5 in URECs from a patient with Joubert syndrome with compound heterozygous mutations in CEP290 mitigated the elongated cilia phenotype observed in these cells." (PMID 34055783, 2021). "Mutations in AHI1 and CEP290 are both a frequent causes of Joubert syndrome and genetic variants in both genes may act as modifier alleles, especially in regard to a retinal and CNS phenotype." (PMID 23028714, 2012).
Joubert syndrome (continued). "The phenotype spectrum of CEP290 related retinal dystrophies is rather broad and includes also syndromic diseases such as Senior-Loken syndrome, Joubert syndrome, Bardet-Biedl syndrome or Meckel-Grüber syndrome." (PMID 37642804, 2023). "Modulation of this pathway with the Hh agonist purmorphamine reconstituted impaired spheroid formation in collecting duct cells from Cep290-mutant mice and in URECs derived from a patient with Joubert syndrome as well the elongated cilia phenotype." (PMID 34055783, 2021). "Few LCA-associated genes like CEP290, ALMS1, IFT140, and IQCB1 also contribute to other syndromes such as Joubert syndrome, peroxisomal disease, Alstrom syndrome, Batten disease, and Senior Loken syndrome with similar ocular manifestations as observed in LCA." (PMID 33957996, 2021). "Truncating mutations in the centrosomal protein of 290 kDa (CEP290) gene (12q21.32) were identified as a novel gene in 2006, and as the most common cause of NPHP associated with Joubert Syndrome and related diseases." (PMID 34828368, 2021). "A Cep290-gene trap mouse model of Joubert syndrome revealed increased Gli3 repressor isoform in the kidney, in agreement with decreased Hh signaling." (PMID 34055783, 2021). "Here, we designed a spliceosome mediated pre-mRNA trans-splicing strategy to rescue expression of CEP290, which is associated with Leber congenital amaurosis type 10 (LCA10) and several syndromic diseases including Joubert syndrome." (PMID 30195768, 2018). "Mutations in the CEP290 gene underlie NPHP6 and are the leading cause of Joubert syndrome and related diseases, a cerebello–retinal–renal syndrome." (PMID 29379777, 2017). "In Joubert syndrome patients, the most common genetic abnormalities are mutations in CEP290 (NPHP6)." (PMID 25974046, 2015). "Cilia in the Cep290−/− mouse model are very short and scarce; cystic kidneys form and progress from birth, as in humans with Joubert syndrome." (PMID 25974046, 2015). "In this study, one patient from family OFT-00177 with EoHM and retinal dystrophy had two VUS, one in CEP290 (a gene related to Bardet-Biedl syndrome, Meckel syndrome, Joubert syndrome and Senior-Løken syndrome) and the other in PCDH15 (a gene responsible for Usher syndrome)." (PMID 35457050, 2022). "Mutation in CEP290 leads to LCA, Bardet–Biedl syndrome, Senior–Loken syndrome and Joubert syndrome." (PMID 33957996, 2021). "Furthermore, CEP290 mutations lead to a range of ciliopathy syndromes with variable clinical manifestations in humans: BBS, Joubert syndrome and Meckel-Gruber syndrome." (PMID 30845169, 2019). "CEP290 mutations were found in 20 patients with LCA and two patients with Joubert syndrome." (PMID 30374144, 2018). "Mutations in ciliary proteins such as CEP290, ARL13B or INPP5E in Joubert syndrome may lead to important neurological disturbances in cerebellar development and defective formation of adult neuronal stem cells regions." (PMID 23205631, 2013). "In contrast, mutations in the gene CEP290, which a cilia protein expressed in PRs and other ciliated cells, can cause a wide range of diseases, including nonsyndromic LCA10 as well as Bardet–Biedl syndrome, Joubert syndrome, Senior–Loken syndrome, and Meckel–Gruber syndrome." (PMID 36074935, 2022). "Notably, basal bodies are formed in both Cep290rd16/rd16 (a model of CEP290-LCA) and Cep290−/− (a model of more severe Joubert syndrome) mouse models, with rudimentary cilia observed only in the milder Cep290rd16/rd16 retina." (PMID 36084637, 2022).
retinal degeneration (42 papers, 2007 to 2025). Degeneration of the retina. "CEP290 is a pivotal protein for ciliary function, with mutations linked to a variety of ciliopathic symptoms including brain malformations, retinal degeneration and renal cyst formation." (PMID 40570958, 2025). "A homozygous mutation in the centrosomal protein 290 (CEP290) gene causes retinal degeneration leading to blindness or severe vision loss at birth or shortly thereafter." (PMID 41476860, 2025). "This highly conserved domain is predicted to bind to microtubules as well as proteins linked to retinal degeneration and ciliary trafficking, such as CEP290, OFD1, and LCA5." (PMID 36233334, 2022). "EDIT-101 is for Leber congenital amaurosis (LCA) 10, a form of inherited retinal degeneration caused by a point mutation in the CEP290 gene." (PMID 35668433, 2022). "The Cep290rd16 (rd16) mouse harbors a mutation in the centrosomal protein Cep290 that results in early-onset retinal degeneration with autosomal recessive inheritance." (PMID 32123325, 2021). "In the present work, we show that reducing the gene dose of Cep290 in Nphp1gt/gt mice exacerbates protein mislocalization and causes retinal degeneration that continues in mature retinas." (PMID 33961633, 2021). "Mutations in human CEP290 are associated with several syndromic and nonsyndromic forms of retinal degeneration." (PMID 32123325, 2021). "Despite the major disruptions in CC structure and rapid retinal degeneration caused by the CEP290 mutations, their effects on the initial stages of cilium formation and localization of other ciliary proteins appear to be less severe." (PMID 34520396, 2021). "The four patients with CEP290 gene mutations showed retinal degeneration, and the two patients with TMEM67 gene mutations had liver diseases." (PMID 33432080, 2021). "The LCA10 genetic disease is a common form of inherited childhood blindness caused by c.2991+1655A>G mutation in CEP290 gene, that results in the retinal degeneration." (PMID 32630614, 2020). "Abyssinian cats exhibit a high degree of inherited retinal degeneration due to the rdAc allele in the feline Cep290 gene and this rdAc allele can also be found at elevated frequencies in several other cat breeds." (PMID 30970040, 2019). "Mutations in AHI1 and CEP290, genes critical to primary cilia function, have been linked to retinal degeneration." (PMID 30518138, 2018). "The genetic defect causative of retinal degeneration in Abyssinian cats has been identified as a single base pair change in intron 50 of the centrosomal protein 290 (CEP290) gene (IVS50+ 9T>G)." (PMID 28928775, 2017). "For cats, PRA is observed less frequently, although recently, a mutation in the CEP290 gene was shown to be causative of hereditary retinal degeneration in a large number of cat breeds, primarily Abyssinian and Siamese cats." (PMID 22550515, 2012). "Another such gene working in concert with RPGRIP1 is CEP290, and when mutated it was found to cause hereditary retinal degeneration in cats." (PMID 22550515, 2012). "Although near or complete loss of CEP290 in our mutant mice results in rapid retinal degeneration and severe phenotypes throughout multiple tissues, nascent photoreceptors in the mutant retina are still able to form cilia with at least a subset of normally localized CC proteins." (PMID 34520396, 2021). "In addition to LCA, different CEP290 mutations can give rise to nonsyndromic retinitis pigmentosa and multisyndromic disorders with associated retinal degeneration, such as Bardet-Biedl syndrome and Meckel-Gruber syndrome." (PMID 34520396, 2021). "Mice lacking RPGR were crossed to a line with a mutation in the gene encoding centrosomal protein 290 (CEP290), resulting in double homozygotes with a more severe and rapid progression of retinal degeneration, indicating a genetic interaction between RPGR and CEP29016." (PMID 32704025, 2020). "CEP290 mutations are the most common inherited cause of retinal degeneration (LCA)." (PMID 29379777, 2017).
retinal degeneration (continued). "Furthermore, the mild phenotypes observed in cep290fh297/fh297 mutants was not due to retinal regeneration These data demonstrate a role for Cep290 in cone survival in zebrafish and provide a foundation for future analysis of potential modifier genes of cep290-associated retinal degeneration." (PMID 30970040, 2019). "This disease is associated with the c.2991 + 1655A > G mutation in intron 26 of the CEP290 gene (known as the IVS26 mutation), which leads to retinal degeneration and progressive vision loss." (PMID 40869487, 2025). "EDIT-101 utilizes CRISPR–Cas9 technology to remove the defective sequence in the CEP290 gene and halt retinal degeneration." (PMID 40869487, 2025). "Naturally occurring SLSN-causing mutations in genes such as CEP290 and ICQB1 have been identified in retinal degeneration cat models." (PMID 40427560, 2025). "CEP290 gene mutations are linked to Joubert syndrome-related disorders (JSRD) which present with various symptoms, including brain malformation, retinal degeneration, and kidney disorders." (PMID 40570958, 2025). "Zebrafish cep290 mutants display variable axis curvature defects at embryonic stages as well as slow retinal degeneration, and develop juvenile scoliosis." (PMID 39388365, 2024). "Previous work had demonstrated that both cep290 and bbs2 mutants undergo slow retinal degeneration with increased retinal inflammation." (PMID 37293546, 2023). "Consistent with the mouse, some cep290 null zebrafish are viable and display adult retinal degeneration." (PMID 36533556, 2022). "In Cep290 mouse mutants, the rd16 line lacking exons 35 to 39 (in-frame deletion of 897 bp) shows only retinal degeneration, whereas the Cep290 knockout mouse showed retinal degeneration and also hydrocephalus, kidney cysts and cilia axoneme defects." (PMID 34155518, 2021). "Our study further shows that reduction of Cep290 gene dose exacerbates protein confinement defects and retinal degeneration in Nphp1 mutants." (PMID 33961633, 2021). "The CC develops in CEP290 mutants prior to retinal degeneration." (PMID 34520396, 2021). "This lack of presumed functionality is supported by the lack of clinical characteristic in OB2 of patients with CEP290 mutations such as retinal degeneration, hypogonadism, polydactyly, renal dysfunction and MR." (PMID 31488071, 2019). "For example, a spontaneous mutation in Gpnmb, a gene that contributes to pigmentary-related eye diseases, is known to have been fixed in the DBA/2J stock and an in-frame deletion in centrosomal/ciliary protein Cep290 that produces retinal degeneration was fixed in BXD24." (PMID 29403379, 2017). "It is interesting that a 300-amino acid in-frame deletion of NPHP6/CEP290 caused retinal degeneration alone, without renal or cerebellar involvement, in the rds16 mouse model." (PMID 19439065, 2009). "Additionally, the function of CEP290 has been explored by using a mouse model of LCA with a disrupted microtubule-binding domain, which caused significant deficits in cilia formation and retinal degeneration." (PMID 40427560, 2025). "Although both cep290 and bbs2 mutants undergo proliferation of rod precursors in response to retinal degeneration, the process of negatively regulating proliferation is enriched for upregulated genes, and this negative regulation may restrict proliferation of Müller glia and inhibit regeneration." (PMID 37293546, 2023). "Furthermore the cep290fh297/fh297 mutant represents a model for slow retinal degeneration that mimics the ocular involvement of CEP290-dependent LCA and provides a unique platform to screen for genetic modifiers that accelerate or prevent photoreceptor degeneration." (PMID 30970040, 2019). "We further show that Nphp1 genetically interacts with Cep290, another NPHP gene, and that a reduction of Cep290 gene dose results in retinal degeneration that continues until adulthood in Nphp1 mutant mice." (PMID 33961633, 2021).
retinal degeneration (continued). "At 2 months of age, when Nphp1gt/gt;Cep290+/+ mice exhibited no mislocalization and no degeneration, Nphp1gt/gt;Cep290+/fl mice exhibited severe retinal degeneration with only 3–5 rows of photoreceptor cell nuclei remaining." (PMID 33961633, 2021). "The total amount of aberrant Cep290 transcripts (containing either exon X, exon Y or exons X + Y) did not exceed ~15% of the total pool of Cep290 transcripts, and therefore did not result in any signs of retinal degeneration in our mouse model." (PMID 25761237, 2015).
Retinal dystrophy (27 papers, 2010 to 2025). Retinal dystrophy is an abnormality of the retina associated with a hereditary process. "Mutation in the CEP290 gene is a significant factor contributing to retinal dystrophy or congenital blindness, with all CEP290 mutations showing some degree of retinopathy." (PMID 38671609, 2024). "Background/Objectives: Biallelic pathogenic variants in the CEP290 gene are typically associated with severe, early-onset inherited retinal dystrophies (IRDs) in both syndromic and non-syndromic forms." (PMID 39766851, 2024). "LCA10 is a severe form of retinal dystrophy caused by an adenine to guanine point mutation within intron 26 of the human CEP290 gene (IVS26)—resulting in the inclusion of a cryptic exon and a premature stop codon." (PMID 36792602, 2023). "The clinical and genetic findings of CEP290-associated retinal dystrophy seen at our clinical site have been previously published by our group." (PMID 37240262, 2023). "The disease-associated variants for retinal dystrophies screened in this study include CEP290, KIF3B and AIPL1." (PMID 35709088, 2022). "So far, retinal organoids derived from patient-specific iPSC were reported to model, at some degree, phenotypes of retinal dystrophy, such as CEP290 and NR2E3 gene mutation-related LCA." (PMID 31572124, 2019). "LCA10 caused by mutations in the CEP290 gene is a severe retinal dystrophy." (PMID 32292501, 2020). "Interestingly, several studies have recently shown in retinal dystrophy patients, with nonsense mutations in CEP290, that mild retinal phenotypes are associated with nonsense-mediated alternative splicing or endogenous basal exon skipping." (PMID 31346239, 2019). "In addition to CEP290, several other of the most frequently mutated inherited retinal dystrophy genes, e.g., ABCA4, EYS, and USH2A have a cDNA size way exceeding this limit and hence are not amenable for AAV-based gene therapy." (PMID 26325627, 2015). "Typically, the CEP290-related phenotype presents an early onset retinal dystrophy or LCA, or a severe cone–rod-type retinal dystrophy." (PMID 37642804, 2023). "CEP290 is termed “a gene with many faces” for its broad phenotypic spectrum, which involves retinal dystrophy, renal disease, hepatic disease, cardiac disease, encephalocele, and situs inversus." (PMID 36468023, 2022). "Ten families had variants in genes related to a syndromic disease with retinal dystrophy (COL9A1, CEP290, PCDH15, LRP5, PEX1, CFH, COL2A1 and COL11A1)." (PMID 35457050, 2022). "Early molecular diagnosis of CEP290-related retinal dystrophy is critically important, because this allows the provision of better informed advice on prognosis and will prompt further investigation to rule out associated systemic disease." (PMID 29398085, 2018). "Several patients with CEP290-related retinal dystrophy showed additional systemic features." (PMID 20683928, 2010). "To date, proof‐of‐concept of AONs has been shown in both cell‐based models and animal models for four retinal dystrophy genes: CEP290, CHM (Garanto, van der Velde‐Visser, Cremers, & Collin, 2018), RHO, and USH2A, and represents a promising therapy for retinal dystrophies." (PMID 30950243, 2019).